PDGFRB (platelet derived growth factor receptor beta)
Diseases named in the same sentence as PDGFRB in open-access papers (continued):
Sharing a sentence is not in itself a finding about the gene and the disease.
infection (27 papers, 2008 to 2026). The state of being infected such as from the introduction of a foreign agent such as serum, vaccine, antigenic substance or organism. "Indeed, infection with the adenoviral construct encoding the dominant-negative form of Pdgfrβ effectively reduced the expression of fibrosis-related genes in fibrotic rPCLS." (PMID 40869104, 2025). "For this we performed immunohistochemistry on brain sections obtained from mice before infection, as well as 18 and 42 h after infection using pericyte markers PDGFRβ and CD13." (PMID 37978545, 2023). "Our findings that PDGFRβ is important for JEV infection and that the approved drug imatinib blocks the infection suggest that an effective repurposing of PDGFRβ inhibitor is a possible treatment strategy for JEV infection." (PMID 33753340, 2021). "These αSMA+, Gli1+, PDGFRβ + cells are visible in the post‐pyelonephritic scar as it forms and matures, and they become the predominant producers of TGFβ1 during resolving infection." (PMID 32227630, 2020). "At day 7 post-infection, mice were sacrificed and brain microvessels were isolated and stained for platelet-derived growth factor receptor β (PDGFRβ; a pericyte marker) and p24 (an indicator of active infection)." (PMID 29311803, 2017). "Immunohistochemical analysis of brain sections obtained from mice 42 h post-infection revealed a significant decrease in anti-PDGFRβ staining in TAM-treated PDGFRB::creER2-iDTA mice compared to those given corn oil, reflecting the efficacy of our cell depletion approach." (PMID 37978545, 2023). "Interestingly, we also observed engulfment of Pdgfrβ cells and fragments by Iba+ phagocytes at late stages of T3A infection (arrows)." (PMID 31387911, 2019). "Recent studies have shown that brain platelet-derived growth factor receptor β (PDGFRβ) cells, including pericytes, may act as early sensors of infection by secreting monocyte chemoattractant protein-1 (MCP-1), which transmits inflammatory signals to the central nervous system." (PMID 39862276, 2025). "Therefore, MadCAM-1+ cells and perivascular PDGFRβ+ cells expand during STm infection." (PMID 36950118, 2023). "Thus, it is highly likely that the interactions of TRAP with αvβ3 and PDGFRβ are distinct and might serve different biological functions during the infection process." (PMID 34059712, 2021). "We performed analogous infections in TC‐treated Gli1‐tdTomato+ mice, and the resulting scars contained streaks of activated myofibroblasts, which stained positively for αSMA, Gli1 (via the Tomato fluorophore), and PDGFRβ, and were surrounded by areas of dense collagen deposition." (PMID 32227630, 2020). "Notably, infections with both JEV AT31 and SA14-14-2 were reduced in ΔPDGFRβ cells, suggesting that both the virulent and attenuated JEV strains were sensitive to PDGFRβ." (PMID 33753340, 2021). "In contrast to EphA2, PDGFRβ is downregulated during Ctr infection and no significant changes were observed for PDI or EphB4 expression, suggesting that EphA2 is specifically upregulated and activated during Ctr infection." (PMID 25906164, 2015). "NRP1- and NRP2-targeted knockdown using shRNA infection in these cells significantly decreased PDGFRα and PDGFRβ tyrosine phosphorylation without affecting total PDGFR levels." (PMID 26410366, 2015). "Our results indicate that during infection, C. trachomatis-induced activation of PDGFRβ is not necessary for activation of Abl kinase even though PDGFRβ signaling has been shown to activate Abl kinase in other settings." (PMID 18369471, 2008). "Also, co-silencing EphA2 together with PDGFRβ had no additive effect, suggesting that Ctr does not employ the PDGFRβ during mid-phase infection." (PMID 25906164, 2015).
infection (continued). "Alongside these effects after infection, mature FDC networks are strikingly absent, whereas immature FDC precursors, including marginal sinus pre-FDCs (MadCAM-1+) and perivascular pre-FDCs (PDGFRβ+) are enriched." (PMID 36950118, 2023). "PDGFRβ correlated negatively in BSIII–IV and positively in BSV–VI with several cytokines (IL-10, IL-12, IL-13, IL-2, IL-4 and TNF-α) but only in the absence of infection." (PMID 33723589, 2021).
hematologic malignancies (15 papers, 2008 to 2026). "TEL fusion proteins with other tyrosine kinases, such as ABL1, ABL2, JAK2, NTRK3, FFGR3, and PDGFRB, have also been associated with various hematologic malignancies, though direct comparisons between these fusion proteins in mouse models is not complete." (PMID 24116232, 2013). "CCDC88C encodes a protein part of the Wnt signaling pathway and has previously been described in hematological malignancies as fusion partner to FLT3 and PDGFRB." (PMID 36704135, 2023). "In hematological malignancies, MYO18A has been found as fusions with FGFR1, PDGFRB, and MLL in other hematopoietic malignancies." (PMID 30559310, 2018). "Genomic characterization of pediatric hematologic malignancies in our cohort identified potential therapeutic targets in nearly 40% of patients (7/18, 38.9%), including the consideration of inhibitors targeting MEK (n=3), receptor tyrosine kinases (ALK n=2, PDGFRB n=1), FLT3 (n=1), and PD-L1 (n=1)." (PMID 39687881, 2024).
cardiovascular disease (8 papers, 2013 to 2025). "The results establish a foundation for the further clinical development of PDGFRβ-targeted molecular imaging in cardiovascular disease and potentially beyond." (PMID 41471324, 2025). "In conclusion, we report the successful development, GMP-compliant production, and translational validation of [68Ga]Ga-ATH001, a novel Affibody-based PET radiopharmaceutical targeting PDGFRβ for imaging fibrotic remodeling in cardiovascular disease." (PMID 41471324, 2025). "In summary, how mitophagy is regulated by DRP-1 under pathologic status is critical and complex, which may contribute to the development of specific therapeutic interventions in cardiovascular diseases patients, for example Masatinib, the inhibitor of PDGFRβ." (PMID 37980402, 2023). "Take a comprehensive view of the whole text, how mitophagy is regulated by DRP-1 under pathologic status is critical and complex, which may contribute to the development of specific therapeutic interventions in cardiovascular diseases patients, for example Masatinib, the inhibitor of PDGFRβ." (PMID 37980402, 2023).
adenocarcinoma (7 papers, 2012 to 2025). A common cancer characterized by the presence of malignant glandular cells. "PDGFRβ was an independent predictor of poor survival in the overall Norwegian cohort and an independent predictor of increased survival in the ADC (adenocarcinoma) subgroup of the Swedish cohort." (PMID 31308421, 2019).
neurodegenerative disease (7 papers, 2015 to 2025). A disorder of the central nervous system characterized by gradual and progressive loss of neural tissue and neurologic function. "Targeting PDGF-B/PDGFRβ signaling has been effective in models of neurovascular/neurodegenerative diseases." (PMID 37601628, 2023). "The present findings provided a novel insight into the functional role of direct interaction of EphA4 and PDGFRβ in neurogenesis, implicating its potential use for treating neurodegenerative diseases." (PMID 32116646, 2020). "Primary Familial Brain Calcification (PFBC), a neurodegenerative disease characterized by progressive pericapillary calcifications, has recently been linked to heterozygous mutations in PDGFB and PDGFRB genes." (PMID 26599395, 2015).
hematologic neoplasms (4 papers, 2019 to 2021). "After the detection of PDGFRB rearrangement, imatinib was given at a dose of 400 mg/day, since previous studies have reported a positive outcome from this dose in patients with hematologic neoplasms with PDGFRB rearrangement." (PMID 30697976, 2019). "Because hematologic neoplasms with PDGFRB-fusion genes can be treated with tyrosine kinase inhibitors, the detection of such novel fusions may be clinically important." (PMID 31161074, 2019).
Renal Disease (4 papers, 2012 to 2021). "Anti-TGFβ antibody prevented AA-induced PDGFRβ+ perivascular cell accumulation accordingly to the hypothesis that TGFβ mediates the progression of renal diseases through destabilization of the microvascular network." (PMID 27379382, 2016).
retinopathy (4 papers, 2013 to 2020). "Therefore, loss of PDGFRβ signaling in human retinopathies is expected to induce BRB leakage." (PMID 30150707, 2018). "PDGF-BB has been reported to be involved in astrogliosis and the formation of proliferative membranes in retinopathy by activating PDGFRα and PDGFRβ." (PMID 33323553, 2020). "In support of this, recent investigations in a mouse model of retinopathy showed over-activation of PDGF-B/Pdgfrβ signaling results in excessive pericyte coverage in the retina and promotes the formation of neovascular tufts, which are indicative of endothelial cell over-proliferation." (PMID 30568578, 2018).
vasculopathy (4 papers, 2011 to 2024). "Taken together, our work identified evident vasculopathy and PDGFRβ deficiency in 8-10mo 5xFAD mice." (PMID 38475929, 2024). "Interestingly, we found significant differences in the expression of PDGFRβ and NG2 accompanied with similar hypoperfusion and BBB breakdown in this mouse model, suggesting that pericytes indeed took an important part in Aβ-induced vasculopathy." (PMID 38475929, 2024).
brain disease (3 papers, 2016 to 2024). "PDGFRβ is critical for pericyte function but is reduced in brain disorders that exhibit BBB and BSCB damage." (PMID 27654972, 2016).
inflammation (3 papers, 2014 to 2016). Aberrant reaction of the microcirculation characterized by movement of fluid and leukocytes from the blood into extravascular tissues. "To evaluate the impact of impaired PDGFRβ signaling on allergic inflammation, we treated mice with the tyrosine kinase inhibitor CP-673451, which selectively inhibits PDGFRβ, in the context of HDM exposure for a period of 3 consecutive wk." (PMID 25637607, 2015). "Because PDGFRβ is critical for pericyte function and its removal leads to BBB leakage, our results pinpoint a mechanism linking chronic brain inflammation to BBB dysfunction." (PMID 27654972, 2016).
cardiac disease (2 papers, 2014 to 2016). "As the presence of these cells could be relevant for pathological processes such as fibrosis or valve calcification, future work should explore the role of PDGFRβ+ PDGFRα+ NG2− cells in cardiac disease and in processes involving endothelial–mesenchymal transition." (PMID 27516371, 2016).
respiratory diseases (2 papers, 2023 to 2024). "Considering IM, a higher frequency of respiratory disorders was shown possibly due to its kinase inhibition of PDGFRβ, which is expressed in pericytes and is involved in angiogenesis." (PMID 36980737, 2023).
PDGFRB also shares sentences with these, for which no sentence is quoted: idiopathic pulmonary fibrosis (19 papers); soft tissue sarcoma (15); fibrosarcoma (11); chondrosarcoma (10); chronic eosinophilic leukemia (10); astrocytoma (9); head and neck squamous cell carcinoma (6); hypereosinophilic syndrome (6); malignant glioma (6); acute leukemia (5); ependymoma (5); gastrointestinal tumor (5); systemic mastocytosis (5); Thrombocytopenia (5); chronic kidney disease (4); cutaneous melanoma (4); Hypercholesterolemia (4); juvenile myelomonocytic leukemia (4); leiomyosarcoma (4); Lewis lung carcinoma (4); neurological disorders (4); acute kidney injury (3); adenoma (3); Basal ganglia calcification (3); brain cancer (3); differentiated thyroid carcinoma (3); endometriosis (3); gastric tumour (3); HCMV infection (3); Hypoglycemia (3).
A further 262 diseases each share a sentence with PDGFRB in 3 papers or fewer.